INS (insulin)
Diseases named in the same sentence as INS in open-access papers (continued):
Sharing a sentence is not in itself a finding about the gene and the disease.
metabolic disorders (continued). "The data indicate that the concentration of insulin increases in cows that lost BCS; however, it is possible that a negative energy balance causes the cows to become insulin resistant, an early warning sign of metabolic disease." (PMID 31861177, 2019). "Genes expressed under each pathway need further investigation as they draw a roadmap and possible targets connected specifically to FAK and Insulin signaling pathway to reverse the adipogenic differentiation and potential utilization in the treatment of adipogenesis-related metabolic disorders." (PMID 29298881, 2018). "CORE-IS genes with established links with insulin biology or metabolic disease." (PMID 29986096, 2018). "While causal factors for adverse neonatal anthropometric outcomes are intensively studied, determinants of cord-blood insulin and leptin are less considered in clinical studies, although probably even more important mechanistically for the long-term development of metabolic disorders." (PMID 29925339, 2018). "The insulin signal transduction machinery has been explained in detail over the past few decades and the existence of molecular defects in the pathways activated by insulin, which contribute to metabolic disorders, are undeniable." (PMID 29535681, 2018). "Both of these metabolic disorders are characterized by defects of insulin action." (PMID 30211231, 2018). "As a convergent node in insulin signaling cascade and a master regulator of homeostasis, deregulation of mTOR signaling, including mTORC2, impairs insulin signal transduction and its biological actions, leading to metabolic disorders, including T2DM." (PMID 30510625, 2018). "We independently identified many known IS regulators, including GRB14, a receptor tyrosine kinase adaptor protein which inhibits insulin signaling, located at a GWAS significant metabolic disease loci, while providing the first detailed map of the relationship between lncRNAs and IS." (PMID 29986096, 2018). "Insulin and 17β-estradiol (E2) relieve the vascular complications observed in metabolic disorders." (PMID 29670459, 2018). "We here provide evidence on how chaperones are crucial players for mitostasis and brain insulin sensitivity and on how their impairment leads to mitochondrial dysfunction and may link neurodegenerative and metabolic diseases." (PMID 29755410, 2018). "Dysregulation of insulin signaling is common in metabolic disorders." (PMID 29373583, 2018). "Since CFM formation requires only one minute of NAS feeding, a prolonged treatment could lead first to CFM formation, and then to a metabolic disorder through the insulin/NPF pathway." (PMID 29180783, 2017). "Type 2 diabetes (T2D) is a complex metabolic disease characterized by increased resistance to insulin in several tissues, including liver, adipose tissue, and skeletal muscle, leading to abnormally high blood glucose levels and compromised pancreatic insulin secretion." (PMID 28545587, 2017). "Metabolic diseases are characterized by a decreased action of insulin." (PMID 29203791, 2017). "All these data suggest that this protein could be involved in the decrease in insulin signaling observed in metabolic diseases." (PMID 29203791, 2017). "The present finding that chronic consumption of Reb-A does not impair insulin action is different from other studies in animals and humans demonstrating that artificial sweeteners are associated with metabolic disease." (PMID 28475596, 2017). "In subgroup analysis, fish oil supplementation could benefit insulin sensitivity among people who were experiencing at least one symptom of metabolic disorders (SMD 0.53, 95% CI 0.17 to 0.88, p < 0.001)." (PMID 28673352, 2017). "It has previously been shown that consumption of walnuts does not lead to increased body weight or BMI, may facilitate weight loss, and may have beneficial effects on insulin sensitivity, both in the healthy population and patients with metabolic disorders." (PMID 28686204, 2017).
metabolic disorders (continued). "Insulin signaling is regarded as a major contributor to this phenomenon; much less is known about the role of heparan sulfate-degrading enzyme heparanase in the link between metabolic disorders and cancer." (PMID 28038446, 2017). "Since aqueous extract of Ilex latifolia Thunb improved insulin sensitivity and ameliorated metabolic disorders, we next examined whether Ilex latifolia Thunb could prevent low-grade inflammation in mice under HFD conditions." (PMID 29116160, 2017). "Broad-spectrum therapeutic efficacy and medicinal properties of fenugreek seeds on metabolic disorders have been demonstrated in animal studies that suggest that fenugreek may also contain a constituent which stimulates insulin production or sensitization." (PMID 27733237, 2016). "Nonetheless, it functions as transcriptional regulator for glucose homeostasis and lipid metabolism which is proven to act as a lipid sensor and is a potential therapeutic target to treat metabolic disease and regulated glucose metabolism and insulin sensitivity." (PMID 27625609, 2016). "T2D is a complex metabolic disorder that is characterized, inter alia, by progressive failure of pancreatic β cells to produce insulin, but also by functional or morphological modifications of others organ, such as liver, adipose tissue and the cardiovascular system." (PMID 27153060, 2016). "The higher insulin concentration in the PTX group than in the HFG group might partially have contributed to the mitigation of metabolic disorder in the HFD/STZ mice." (PMID 27612024, 2016). "DM is a group of metabolic disorders characterized by high blood sugar levels over a prolonged period resulting from either destruction or impairment of insulin-secreting pancreatic β cells and insulin action in target tissues." (PMID 27092490, 2016). "However, there were several specific to certain diseases; DNA repair pathways and cancer, circadian rhythm and psychological diseases, and insulin signaling and several metabolic pathways specific to metabolic disorders." (PMID 27656641, 2016). "However, we are not aware of defects in the processing of pre‐proendothelin‐1 to ET‐1 with insulin stimulation or metabolic disease." (PMID 27796268, 2016). "The effects of D-galactose on aging could be attributed to glucose and 1ipid metabolic disorders, oxidative damage, accumulation of advanced glycation end products (AGEs), reduction in abnormal substance elimination, cell apoptosis, and insulin resistance." (PMID 26176541, 2015). "The interplay of intracellular lipid metabolism, chronic inflammation, insulin resistance and cytoskeletal rearrangements might be important in the pathogenesis of microvascular complications of metabolic diseases." (PMID 26545114, 2015). "These information together suggest that ADTRP may be involved in insulin-mediated metabolism regulation and metabolic disorders, such as CAD." (PMID 26375920, 2015). "In this review, we consider how disruption of normal fetal growth may impact skeletal muscle metabolic development, ultimately leading to insulin resistance and decreased insulin sensitivity, a key precursor to later life metabolic disease." (PMID 25685986, 2015). "Liraglutide could exhibit favorable effects on the pathogenesis of metabolic disorders in patients with type 2 DM by increasing insulin sensitivity as an extrapancreatic action." (PMID 25922845, 2015). "Given that GLUT4 is highly abundant in skeletal muscle and is associated with enhanced glucose disposal and insulin action, there has been extensive interest in therapeutic strategies to increase AKT and GLUT4 expression in cohorts at risk of developing metabolic disorders." (PMID 26030423, 2015). "Taken together, our findings suggest that IPP and VPP exert insulin-mimetic adipogenic effects and prevent inflammatory changes in adipocytes, which may offer protection against metabolic disease." (PMID 25714093, 2015).
metabolic disorders (continued). "Gender plays a role in the development of a number of cardiovascular and metabolic diseases and it has been suggested that females may be more insulin resistant in utero." (PMID 26368559, 2015). "In this study, whether there are different expressions of IL-1β, IL-18, and IL-22, which had been reported to be involved in metabolic disorder and insulin sensitivity, is interesting but yet investigated." (PMID 26681840, 2015). "We have concluded from these studies that insulin resistance, rather than body fat per se, is the primary patho-physiological factor leading to metabolic disease risk in youth as it is in adults." (PMID 24433565, 2014). "Further, Eln+/−; ApoE−/− mutants have significant impairment of insulin sensitivity by insulin tolerance testing, independent of body weight or diet, suggesting that elastin insufficiency predisposes to metabolic disease in susceptible individuals." (PMID 26167199, 2014). "The term DM describes a metabolic disorder of multiple aetiologies characterized by chronic hyperglycaemia with disturbances of carbohydrate, fat, and protein metabolism resulting from defects in insulin secretion, insulin action, or both." (PMID 25093193, 2014). "In lean individuals, anti-inflammatory adipokines mediate physiological functions, whilst in states of metabolic diseases, the proinflammatory adipokines modulate insulin resistance either directly by affecting the insulin signaling pathway or indirectly via stimulation of inflammatory pathways." (PMID 24455420, 2013). "TFL consumption might have a beneficial effect on metabolic disorder in relation to decreased plasma insulin and improved insulin sensitivity." (PMID 23476149, 2013). "Therefore, managing these metabolic disorders by administering insulin sensitizers and lipid modulators has been examined to increase the therapeutic response of standard treatments." (PMID 22701799, 2012). "However, growing evidence supports the concept that AD is fundamentally a metabolic disease with substantial and progressive derangements in brain glucose utilization and responsiveness to insulin and insulin-like growth factor [IGF] stimulation." (PMID 22329651, 2012). "Further FFA analysis and investigation of factors regulating hepatic physiology in the target tissues of insulin may reveal information to further our understanding of metabolic diseases." (PMID 23675238, 2011). "Consequently, impaired leptin and/or insulin signaling activation, as observed in db/db mice, has been proposed as potential link between behavioral and metabolic disorders." (PMID 21949705, 2011). "Moreover, metabolic inflexibility and insulin resistance in skeletal muscle are thought to be major contributors to metabolic disorders." (PMID 21437204, 2011). "Impairment of insulin and glucose metabolism by ERβ may have significant implications for our understanding of hormone receptor-dependent pathophysiology of metabolic diseases, and may be essential for the development of new ERβ-selective agonists." (PMID 18584035, 2008). "Furthermore, the review delineates the emerging avenues in the development of novel peptide-based pharmacotherapies, offering insights into their future potential and acquainting the reader with developments in non-insulin gut-pancreatic peptide signalling-based therapies for metabolic disorders." (PMID 42307179, 2026). "The relatively high levels of these trace elements (Fe, Cu, Zn, and Mn) in dawadawa could suggest potential health benefits such as promoting hematopoiesis, neutralization of free radicals, nutrient metabolism, insulin secretion, and alleviating metabolic disorders." (PMID 41030606, 2025). "Consequently, a thorough understanding of mitochondrial dynamics and their interactions with various cellular components may unveil novel strategies for enhancing insulin sensitivity in individuals suffering from metabolic disorders." (PMID 40862129, 2025).
metabolic disorders (continued). "Furthermore, modulating PIK3R1 activity may also improve insulin sensitivity and metabolic regulation, particularly in metabolic disorders like T2DM." (PMID 40747301, 2025). "Lactate, which is traditionally considered a byproduct of anaerobic metabolism, has emerged as an important molecule in metabolic disorders, and its elevated levels may reflect a shift toward anaerobic glycolysis, which is commonly seen in conditions of insulin resistance and metabolic stress." (PMID 40507103, 2025). "Therefore, personalizing diet plans based on microbiome analysis could enhance insulin sensitivity and reduce ERstress, providing a targeted approach to managing metabolic diseases." (PMID 41567335, 2025). "Thus, our findings suggest that targeting the skeletal muscle clock may represent a novel strategy to restore insulin sensitivity in individuals with metabolic disease." (PMID 40495716, 2025). "Although our participants were free of metabolic disorder diagnoses, a supposed gradation in insulin concentrations in the participants according to their different HNF1A genotypes could offer an explanation for the progression in antioxidant capacity among these participants." (PMID 40573148, 2025). "Our findings suggest a more homeostatic role for SAT in cows with SCK, while VAT presents a pro-inflammatory profile, which might be related to dysregulation of lipid homeostasis and insulin sensitivity, likely contributing, to a higher extent, to the pathogenesis of metabolic disorders." (PMID 40599780, 2025). "Moreover, improvements in QUICKI were also observed among individuals with metabolic disorders and BMI ≥ 30 kg/m2, suggesting that hesperidin may possess regulatory potential for insulin sensitivity in these populations as well." (PMID 41586243, 2025). "AD could be regarded as a metabolic disease mediated in part by brain insulin resistance." (PMID 39273520, 2024). "A longer administration period beyond 4 weeks may be necessary to achieve statistically significant results, as previous research in metabolic disease models suggests that treatment durations of 8 to 12 weeks are required to detect changes in markers such as body weight and insulin." (PMID 39408221, 2024). "Finally, increased insulin granule size may contribute to metabolic disorders by impairing their membrane trafficking at the trans-Golgi network (TGN), which could be involved in BI-1-deficient β-cells." (PMID 38744890, 2024). "A systematic review and meta-analysis demonstrated that chromium picolinate supplementation could significantly reduce body mass index (BMI), fasting insulin, and free testosterone levels in PCOS patients, indicating improvements in metabolic disorders associated with the condition." (PMID 39691364, 2024). "Lifestyle factors associated with OCD, such as reduced physical activity, disruption of circadian rhythms, and sleep disorders, may contribute to the development of metabolic disorders by negatively impacting glucose metabolism and insulin sensitivity, but they are insufficiently understood." (PMID 39796465, 2024). "In contrast to the clearance of glucose from the bloodstream in response to insulin stimulation, exercise-induced glucose uptake into skeletal muscle is unaffected during the progression of insulin resistance, placing physical activity at the center of prevention and treatment of metabolic diseases." (PMID 38339185, 2024). "Moreover, although there have been fewer studies exploring the relationship between BDNF and metabolic disorders, there is evidence of an association between BDNF and the reduction in BMI, waist circumference, glucose, insulin, and risk for T2DM, mainly in Asian populations." (PMID 38997780, 2024). "Also, it is controversial whether insulin signaling diminished by GM3 actually aggravates the pathological conditions in metabolic disorders." (PMID 36827398, 2023).
metabolic disorders (continued). "Thus, agents that mimic the effects of exercise on AMPK activation may improve insulin sensitivity of skeletal muscle in metabolic diseases." (PMID 36915683, 2023). "Because PCOS is closely associated with endocrine and metabolic disorders, to investigate the effect of omega-3 PUFAs on metabolism and endocrine function, we established a PCOS model and assessed serum hormone levels, glucose homeostasis and insulin sensitivity in diverse groups." (PMID 37443082, 2023). "Future studies are warranted to further elucidate the function of insulin signaling and estrogen signaling, especially their cross-talk in specific tissues and at global level, for the purpose of preventing dysfunctional hormone-related metabolic diseases and designing new therapeutic strategies." (PMID 36942499, 2023). "Moreover, it was also suggested that DEHP activates Jun-N-terminal kinase (JNK), promoting the apoptosis of hepatic cells and the inhibition of insulin sensitivity, which may lead to metabolic disorders." (PMID 37367903, 2023). "Furthermore, HS6ST2 knockout mice showed glucose and insulin metabolism disorders." (PMID 37337145, 2023). "Inositols indeed play a key role in the management of metabolic disorders, as evidenced by the literature, which has demonstrated the safety of the dosage of 4 g of inositols in their 40:1 ratio in dysmetabolic patients, highlighting their insulin-sensitizing effect." (PMID 38137721, 2023). "In summary, the effects of fecal enzyme activity on glucose, insulin, and incretin levels are complex and multifaceted, and a better understanding of these effects can induce the development of new approaches to manage glucose metabolism and metabolic disorders." (PMID 36839343, 2023). "Additionally, antidiabetic medications such as metformin, thiazolidinediones (TZDs), dipeptidyl peptidase 4 (DPP-4) inhibitors, and sodium glucose cotransporter 2 (SGLT2) inhibitors are currently used to improve insulin sensitivity and glycemic control in individuals with metabolic diseases." (PMID 37240157, 2023). "In addition, insulin sensitivity is higher in women, which may result in a lower prevalence of metabolic diseases in women." (PMID 36407325, 2022). "Thus, pharmacological strategies aimed at regulating adipocyte hypertrophy (increase in adipocyte size) in favor of promoting hyperplasia (increase in adipocyte number) have the potential to improve adipocyte insulin sensitivity and provide therapeutic benefits in the context of metabolic disorders." (PMID 35163825, 2022). "Thus, further studies are warranted to investigate whether restoring of THRSP responsiveness in insulin-resistant individuals could have therapeutic potential for ameliorating metabolic disease." (PMID 35715726, 2022). "Previous studies have confirmed the association between integrin or AMPK and neurodegenerative disease, and our results showed changes in the integrin and AMPK pathways in insulin resistance-induced neuronal cells, suggesting the possibility that metabolic disease may induce AD." (PMID 35055191, 2022). "Low insulin levels, insulin resistance in target tissues, insulin-receptor expression, especially in adipose tissue and skeletal muscles, and to a lesser extent in the liver, effector enzymes, and/or signal transduction system all can play vital roles in metabolic disorders." (PMID 36557843, 2022). "Additionally, GDF15 has a protective effect against genetic and diet-related obesity.GDF15 overexpression improves insulin sensitivity, and its knockdown enhances blood glucose levels in diabetic rat models, supporting its beneficial effect on metabolic diseases." (PMID 35634503, 2022). "Secondly, under sex hormone-deprived condition, females are generally more susceptible to develop metabolic disorders, whereas males are more susceptible to develop LV and cardiac mitochondrial impairments even in the absence of obese-insulin-resistant condition." (PMID 35301277, 2022).